LEP (leptin)
Diseases named in the same sentence as LEP in open-access papers (continued):
Sharing a sentence is not in itself a finding about the gene and the disease.
ischemic cardiomyopathy (1 paper, 2023). Ischemic cardiomyopathy is a cardiomyopathy in which a weakness in the muscle of the heart due to inadequate oxygen delivery to the myocardium with coronary artery disease being the most common cause. "SGLT1 expression is altered in diabetic and ischemic cardiomyopathy; SGLT1 expression may be partially regulated by leptin, and SGLT1 mediates at least part of the increased cardiac glucose uptake in response to insulin and leptin." (PMID 37047055, 2023).
juvenile dermatomyositis (1 paper, 2025). Juvenile dermatomyositis (JDM) is the early-onset form of dermatomyositis (DM), a systemic, autoimmune inflammatory muscle disorder, characterized by proximal muscle weakness, evocative skin lesion, and systemic manifestations. "Furthermore, a correlation between leptin and total FM has also been found in juvenile dermatomyositis." (PMID 40085146, 2025).
kidney injuries (1 paper, 2024). "Several mechanisms, such as pro-inflammatory signals, oxidative stress, mitochondrial dysfunction, and dysregulation of serum leptin–adiponectin levels, may be responsible for such kidney injuries." (PMID 38732633, 2024).
kidney transplant (1 paper, 2021). A surgical procedure in which one or both kidneys from a donor are implanted into a recipient. "Leptin concentration evaluation in combination with BIA, handgrip strength measurement, and GNRI assessment are tools of importance in defining nutrition status in the early post-kidney transplant period." (PMID 34441040, 2021).
laryngeal squamous cell carcinoma (1 paper, 2022). A squamous cell carcinoma that arises from the larynx. "For example, high leptin levels in tumor samples were related to recurrence of malignancy in laryngeal squamous cell carcinoma." (PMID 35778755, 2022).
lentivirus infection (1 paper, 2018). Virus diseases caused by the Lentivirus genus. "The elevated expression level of leptin-induced by lentivirus infection of hMSCs was confirmed by western blot and immunofluorescence staining targeting leptin." (PMID 29748581, 2018).
leprosy (1 paper, 2025). Leprosy is a chronic infectious disease affecting primarily the skin and peripheral nervous system. "As far as the authors’ knowledge, there were only a few studies reporting serum leptin levels in leprosy patients." (PMID 41239264, 2025). "In leprosy, liposaccharides contained in the outermost layer of the cell wall of M. leprae can stimulate the secretion of leptin." (PMID 41239264, 2025).
Lewis lung carcinoma (1 paper, 2014). "Lewis lung carcinoma did not affect plasma levels of leptin." (PMID 25356654, 2014).
Leydig cell tumor (1 paper, 2020). A sex cord-stromal tumor occurring in the testis and rarely in the ovary. "We revealed significantly increased expression of leptin, adiponectin and their receptors, as well as aromatase in Leydig cell tumors in comparison to control." (PMID 32455738, 2020). "The study found high expression of leptin, adiponectin and their receptors in Leydig cell tumors, which can be considered as possible new diagnostics and therapeutic markers." (PMID 32455738, 2020). "Significantly increased expression of leptin (p < 0.001) and its receptor (p < 0.01) as well as adiponectin (p < 0.01) and its receptor (p < 0.001) was revealed in Leydig cell tumors when compared to control." (PMID 32455738, 2020). "The ratio of ERα to ERβ expression may be an important potential regulatory factor in leptin expression, but it is disturbed in Leydig cell tumors [for review see 28,29]." (PMID 32455738, 2020).
lipidosis (1 paper, 2017). "Moreover, adipocytokines IL6 and Leptin, in addition the genes, EGR1, FOS, SERPINE1, AGT and MMP2 might have great impacts on adipocyte differentiation and lipidosis." (PMID 28706200, 2017).
long-bone fracture (1 paper, 2021). "Higher serum leptin levels associate a low incident of long-bone fracture; the hazard ratio was 0.70, P value = 0.03." (PMID 34796028, 2021).
lumbar disc degeneration (1 paper, 2018). "We constructed a rat model of lumbar disc degeneration and determined that leptin was highly expressed in the presence of CEP calcification." (PMID 29372627, 2018).
lung squamous cell cancer (1 paper, 2010). "Leptin has a stimulatory action on a clonal cell line derived from human lung squamous cell cancer (SQ5 cells), an effect mediated through mitogen activated protein (MAP) kinase activity, indicating that leptin may act as a growth factor." (PMID 21040518, 2010).
lymphoproliferative disorders (1 paper, 2022). "Instead, the more severe side effects, although rare, are lymphoproliferative disorders, anti-leptin antibodies, pancreatitis, hypoglycemia, autoimmunity and immune-related hypersensitivity." (PMID 35600578, 2022). "Metreleptin’s black box warnings are concerns for lymphoproliferative disorders and the production of anti-leptin antibodies." (PMID 35600578, 2022).
malignant glioma (1 paper, 2019). A grade III or grade IV glioma arising from the central nervous system. "We analysed the potential role of leptin and OB-Rb in carcinogenesis of malignant gliomas." (PMID 30803210, 2019).
mastocytosis (1 paper, 2013). A clonal myeloproliferative neoplasm characterized by the proliferation and accumulation of neoplastic mast cells in one or multiple organs or organ systems. "Taken together this suggests that CD4+ T-cells drive a cascade in which I-cell hyperplasia produces hypophagia and weight loss, lowering pro-inflammatory leptin levels which feed back to influence the protective Th2 immune response, augmenting mastocytosis and allowing parasite expulsion." (PMID 23349631, 2013). "We therefore maintained basal leptin levels in infected hypophagic mice and strikingly saw a significant reduction in Th2 cytokines and mastocytosis culminating in delayed worm expulsion." (PMID 23349631, 2013). "A key Th2 driven expulsion mechanism of T. spiralis is mastocytosis and this was seen to be significantly reduced upon the restoration of basal leptin levels analogous to delayed adult worm expulsion." (PMID 23349631, 2013). "Interestingly mastocytosis was similar in both leptin reconstituted and wild-type mice at day 8 p.i. demonstrating that initially mastocytosis can establish, but without the I-cell driven reduction in Th1 polarizing leptin it is blunted later in infection." (PMID 23349631, 2013).
metastatic melanoma (1 paper, 2020). A melanoma that has spread from its primary site to another anatomic site. "Fourth, we did not have a group of patients with distant metastatic melanoma to evaluate their serum TGF-β1 and leptin levels." (PMID 32968152, 2020).
microcephaly (1 paper, 2019). A congenital or acquired developmental disorder in which the circumference of the head is smaller than normal for the person's age and sex. "Moreover, the leptin levels (ng/mL) among the P falciparum–SH and P falciparum–microcephaly groups were lower than those in the noninfected group, although these decreases were not significant." (PMID 31050780, 2019).
Mitochondrial myopathy (1 paper, 2025). "These associations were previously unrecognized but are consistent with a whole-body feed-forward action of mitochondrial myopathy on levels of brain leptin, corticosteroids, and neurotransmitter signaling." (PMID 40100251, 2025).
motor neuron disease (1 paper, 2021). "Moreover, recent studies indicate that reducing leptin levels improves lifespan and reduces motor neuron degeneration in mutant superoxide dismutase 1 (SOD1) mice, suggesting that altering leptin levels mitigates motor neuron disease progression." (PMID 33440796, 2021).
mucositis (1 paper, 2017). Mucositis is inflammation and damage of the mucous membranes lining the mouth and other parts of the gastrointestinal (GI) tract. "Leptin treatment has been shown to promote intestinal recovery and enhance enterocyte turnover in a rat model of methotrexate-induced mucositis." (PMID 29124041, 2017).
muscular atrophy (1 paper, 2009). "Data from our study indicate, for the first time, that leptin treatment prevents muscular atrophy by decreasing FoxO3a, MAFbx and MuRF1 protein expression in relation to an increase in the PGC-1α protein in the GAS muscle of wild type and ob/ob mice." (PMID 19730740, 2009).
Mycobacterium avium infection (1 paper, 2020). "Leptin-deficient mice infected with Mycobacterium avium infection presented lower splenic bacterial load over time and higher activation of T cells." (PMID 32709166, 2020).
myelofibrosis (1 paper, 2018). A partial or complete replacement of the bone marrow stroma by fibrous tissue. "Interestingly, myelofibrosis patients treated with Ruxolitinib show increased plasma levels of leptin, which is an indication of fat mass gain, after only 28 days of therapy." (PMID 29867515, 2018).
narcolepsy (1 paper, 2022). A sleep disorder characterized by a tendency for excessive sleepiness during the day which occurs even after adequate sleep in the nighttime. "It has been suggested that the observed overweight in patients with narcolepsy may be partially attributed to changes in leptin and ghrelin levels." (PMID 36422261, 2022). "However, the role of leptin and ghrelin cannot be neglected, and newly discovered metabolomics may provide future understanding regarding the mechanisms behind weight gain in narcolepsy." (PMID 36422261, 2022). "In conclusion, most of the current evidence does not support a role for leptin and ghrelin secretion in weight gain in patients with narcolepsy." (PMID 36422261, 2022). "A subsequent study reported no changes in the mean 24 h total plasma ghrelin and leptin levels or food-induced suppression of ghrelin concentrations between patients with narcolepsy and healthy controls." (PMID 36422261, 2022). "A study that measured peripheral leptin levels in 42 patients with narcolepsy and 31 BMI-matched controls reported no reduction in peripheral leptin levels in patients with narcolepsy." (PMID 36422261, 2022). "Interestingly, the normal nocturnal acrophase of plasma leptin levels observed in controls was absent in patients with narcolepsy, suggesting a possible circadian rhythm disturbance of leptin secretion in narcolepsy." (PMID 36422261, 2022).
nasopharyngeal tumors (1 paper, 2022). "In addition, the expression patterns of these markers in response to leptin expression could possibly explain our findings of the association between elevated intratumoral expression of leptin and more advanced nasopharyngeal tumors and poor prognosis of NPC." (PMID 35778755, 2022). "The elevated expression of leptin found within nasopharyngeal tumors, raises the intriguing question of the potential causes of elevated intratumoral leptin expression." (PMID 35778755, 2022). "In our study, we show that nasopharyngeal tumors are stained positively for leptin." (PMID 35778755, 2022). "However, it is unclear if the change of NPC cell invasiveness and elevated leptin in more advanced nasopharyngeal tumors that we observed in our experiments have a connection with EMT." (PMID 35778755, 2022). "In our study, although we did not observe a trend toward a higher BMI in patients diagnosed with NPC (data not shown), we found relatively high levels of circulating serum leptin and significant elevated mRNA and protein expression of leptin in nasopharyngeal tumor biopsies." (PMID 35778755, 2022).
neural tube defect (1 paper, 2020). A congenital defect characterized by failure of the neural tube to close completely; this results in the presence of openings in the brain or spinal cord. "More specifically, in different studies, a correlation of maternal serum leptin with AFL has been found in general, or only in neural tube defect pregnancies, or even a lack of correlation has been reported." (PMID 32825787, 2020).
neuroendocrine disorder (1 paper, 2025). A disease or disorder that affects the neuroendocrine gland, any of the organized aggregations of cells that function as secretory or excretory organs and that release hormones in response to neural stimuli. "In addition, the neuroendocrine disorders caused by leptin secreted by visceral adipose tissue and inflammatory cytokines can lead to enhanced noradrenergic sympathetic nerve activity and stimulation of the urothelium." (PMID 40475997, 2025).
neurofibroma (1 paper, 2022). An intraneural or extraneural neoplasm arising from nerve tissues and neural sheaths. "Nevertheless, interestingly, previous studies showed that NF1-associated neurofibromas present neoplastic Schwann cells with lipid droplets accumulation, express leptin and have higher chances of having intermingled adipocytes than non NF1-associated neurofibromas." (PMID 36064430, 2022).
neuroma (1 paper, 2022). A tumor that grows from a nerve or is composed of nerve cells and nerve fibers. "This study aims to investigate the effects of different music on neuroma pain in rats and potential underlying mechanisms mediated by adipokines (leptin)." (PMID 36456983, 2022). "According to the findings obtained in the neuroma pain model, we conclude that graceful music influence leptin concentration both in the peripheral and central nervous systems." (PMID 36456983, 2022).
nonischemic cardiomyopathy (1 paper, 2024). Forms of cardiomyopathy that are not related to known coronary artery disease. "In patients with nonischemic cardiomyopathy, lower leptin levels are associated with an increased likelihood of HTX." (PMID 38339027, 2024).
optic neuritis (1 paper, 2025). Optic neuritis is inflammation of the optic nerve, the nerve that carries the visual signal from the eye to the brain.The conditionmay cause sudden, reduced vision in the affected eye(s). "Similarly, regarding leptin’s prognostic value, one study found that in male MS patients, higher serum leptin was associated with more severe optic neuritis, but not with recovery." (PMID 41516046, 2025).
oral lichen planus (1 paper, 2025). Oral lichen planus is a chronic inflammatory oral condition of unknown aetiology characterized by T-cell-mediated chronic immune response and abnormal epithelial keratinization cycle. "Salivary and serum leptin levels in OLP patients were higher than in healthy control subjects, suggesting their potential role in the diagnosis of oral lichen planus." (PMID 40764478, 2025).
oral squamous cell carcinoma (1 paper, 2023). "A decrease in circulating leptin levels can be detected in patients with cancer, including oral squamous cell carcinoma." (PMID 37620971, 2023).
osteosclerosis (1 paper, 2019). Abnormally high bone density. "Thus, due at least in part to a paucity of adipose derived leptin and adiponectin, congenital absence of fat induces severe osteosclerosis by stimulating bone formation." (PMID 31233501, 2019). "μCT analysis established that absence of both leptin and adiponectin markedly reduces the capacity of WAT to normalize FF osteosclerosis." (PMID 31233501, 2019).
pancreatic disorders (1 paper, 2016). "Other studies showed that offspring consumption of a rich carbohydrate-milk during lactation increased plasma levels of INS and LEP, and also BW, resulting in pancreatic disorders." (PMID 27011203, 2016).
pancreatic neuroendocrine tumor (1 paper, 2025). Pancreatic endocrine tumor, also known as pancreatic neuroendocrine tumor (PNET), describes a group of endocrine tumors originating in the pancreas that are usually indolent and benign, but may have the potential to be malignant. "In a study on pancreatic neuroendocrine tumors, the examined group had the same leptin levels in the serum as controls, with no BMI differences between groups." (PMID 40940878, 2025).
parotid tumors (1 paper, 2022). "In the first study of its kind, researchers identified leptin as a preoperative indicator of parotid tumors; salivary leptin was used to distinguish tumor patients from healthy individuals." (PMID 35628271, 2022).
pemphigus (1 paper, 2014). Pemphigus is a group of rare autoimmune diseases that cause blistering of the skin and mucous membranes (mouth, nose, throat, eyes, and genitals).This conditioncan occur at any age, but often strikes people in middle or older age. "In patients with pemphigus, there were significant correlations between BMI and Box-Cox transformed serum leptin concentrations (r = 0.66, P < 0.0001 in females and r = 0.75, P < 0.0001 in males)." (PMID 24900992, 2014). "The aim of this study was to compare serum leptin levels in recently diagnosed pemphigus patients and healthy controls and to evaluate the clinical characteristics that could be associated with leptin levels." (PMID 24900992, 2014). "Therefore, we presumed that leptin might play a role in the pathogenesis of pemphigus regarding its wide range of effect on T cells." (PMID 24900992, 2014). "The median serum leptin levels were 10.8 ng/mL (IQR: 3.1–23.2 ng/mL; range: 0.1–110 ng/mL) in patients with pemphigus and 12 ng/mL (IQR: 4.9–28.7 ng/mL; range: 0.5–69.9 ng/mL) in healthy controls." (PMID 24900992, 2014). "The results of our study suggest that pemphigus does not have a direct influence on leptin serum levels and it seems that the pathogenesis of pemphigus is not dependent on the connection with adipose tissue or leptin as an adipocyte-derived mediator." (PMID 24900992, 2014).
Peptic ulcer (1 paper, 2016). The term peptic ulcer refers to acid peptic injury of the digestive tract, resulting in mucosal break reaching the submucosa. "Plasma leptin levels and BMI were positively correlated, and active ghrelin levels and atrophic pattern were weakly negatively correlated in peptic ulcer patients." (PMID 27716077, 2016). "(iii) Plasma leptin levels and BMI were positively correlated, and the active ghrelin levels and atrophic pattern were weakly negatively correlated in peptic ulcer patients." (PMID 27716077, 2016). "The increase of plasma leptin levels after eradication in peptic ulcer patients needs explanation." (PMID 27716077, 2016).
pericarditis (1 paper, 2017). An inflammatory process affecting the pericardium. "However, further analysis in patients with SLE showed that the TT genotype and T allele frequencies of the LEP rs2071045 polymorphism were nominally significantly higher in patients with pericarditis (P = 0.012, P = 0.011, respectively)." (PMID 28244652, 2017).
peripartum cardiomyopathy (1 paper, 2022). Peripartum cardiomyopathy (PPCM) is an idiopathic, potentially fatal form of dilated cardiomyopathy that develops during the final month of pregnancy or within five months after delivery. "Maternal obesity increases the risk of peripartum cardiomyopathy; leptin contributes to vascular dysfunction and is hypothesized to contribute to peripartum cardiomyopathy in mothers with obesity." (PMID 35928678, 2022).
peripheral vascular disease (1 paper, 2023). Any disorder affecting blood flow through the veins or arteries outside of the heart. "Recently, it was reported that leptin circulating levels can independently predict CV outcome and all-cause mortality in hemodialysis patients, and this may result from leptin effects on the development of LVH and peripheral vascular disease." (PMID 37189644, 2023).
Peritoneal Fibrosis (1 paper, 2020). Disorder characterized by a wide range of structural changes in PERITONEUM, resulting from fibrogenic or inflammatory processes. "As summarized in this review, tamoxifen has multiple mechanisms of action, including the inhibition of TGF-β1 targets, ERE and HRE, HIF-α, SNAIL, RAGE, VEGF, MMP, PAI-I, Leptin, PARP, peritoneal fibrosis, platelet activation, cell migration, BM/ECM invasion, and neoangiogenesis." (PMID 32532126, 2020).
placental disorder (1 paper, 2018). "For instance, we found hyperacetylation of regions near HK2, FLT1, and LEP, previously reported to be upregulated in other placental disorders, and hypoacetylation of regions near CH2 and CDLN1, which are involved in growth and endothelial cell-to-cell adhesions." (PMID 29983832, 2018).